ENSG00000268442 (hepatitis A virus cellular receptor 1 (HAVCR1) pseudogene)
Synonyms: HAVCR1P1
Gene: Transcribed processed pseudogene on chromosome 19 (24,162,370 to 24,163,425, reverse strand). Ensembl gene ENSG00000268442.
Diseases named in the same sentence as ENSG00000268442 in open-access papers:
ENSG00000268442 is named in the same sentence as 1 disease in open-access papers, as found by Europe PMC text mining. Sharing a sentence is not in itself a finding about the gene and the disease.
ENSG00000268442 shares sentences with these, for which no sentence is quoted: cancer (1 paper).